PERP (p53 apoptosis effector related to PMP22)
Description:
Component of intercellular desmosome junctions (By similarity). Plays a role in stratified epithelial integrity and cell-cell adhesion by promoting desmosome assembly (By similarity). Thereby plays a role in barrier function of the skin against infection (By similarity). Plays a role in mammary epithelial tissue homeostasis and remodeling during and after pregnancy, potentially via its involvement in desmosome cell-cell junctions (By similarity). Required for tooth enamel development via facilitating desmosome-mediated ameloblast adhesion to the stratum intermedium during the transitional stage of amelogenesis (By similarity). May also play a role in downstream transcriptional regulation of other genes involved in amelogenesis such as AMBN, ENAM, MMP20 and KLK4 (By similarity). Positively regulates apoptosis in T-helper 17 (Th17) cell populations via caspase-dependent signaling (By similarity). Promotes neutrophil transepithelial migration in response to chemoattractants such as hepoxilin A3 (HXA3), N-Formylmethionyl-leucyl-phenylalanine (fMLP) and CXCL8/IL-8. Required for neutrophil transepithelial migration in response to S.typhimurium infection. May act as a positive regulator of endothelial cell apoptosis in response to blood flow-derived shear stress (By similarity).
Synonyms: KCP1; KRTCAP1; PIGPC1; THW; dJ496H19.1; EKVP7; OLMS2
Tractability: Antibody: UniProt places it where antibodies can reach, with high confidence; its Gene Ontology location is reachable by antibodies, with high confidence; UniProt predicts a signal peptide or a membrane-spanning region.
Gene: Protein-coding gene on chromosome 6 (138,088,505 to 138,107,419, reverse strand). Ensembl gene ENSG00000112378.
Subcellular location: Cell junction, desmosome; Cell membrane; Cytoplasm
Pathways (Reactome):
Developmental Biology: Formation of the cornified envelope
Gene Ontology:
Molecular function: protein binding
Biological process: positive regulation of neutrophil chemotaxis; positive regulation of proteolysis; cell-cell adhesion; mammary gland duct morphogenesis; positive regulation of T cell apoptotic process; tissue homeostasis
Cellular component: cytoplasm; plasma membrane; cell-cell junction; desmosome; Golgi apparatus; membrane; mitochondrion
Genetic constraint (gnomAD): Loss-of-function variants: 11 observed, 17.82 expected, observed/expected ratio (o/e) 0.62, 90% interval 0.39 to 1.02. The upper end of that interval is the gene's LOEUF score, 1.02, which puts it in group 4 of 6, group 1 being the genes least tolerant of losing a copy. Missense variants: 198 observed, 210.54 expected, observed/expected ratio (o/e) 0.94, 90% interval 0.84 to 1.06. Synonymous variants: 82 observed, 87.37 expected, observed/expected ratio (o/e) 0.94, 90% interval 0.78 to 1.13.
Homologues: Orthologues: chimpanzee PERP (99% identical), macaque PERP (98% identical), pig PERP (97% identical), dog PERP (96% identical), rat Perp (93% identical), guinea pig PERP (91% identical), mouse Perp (91% identical), tropical clawed frog perp (55% identical), zebrafish perp (47% identical), Drosophila melanogaster CG45049 (23% identical), Caenorhabditis elegans vab-9 (18% identical). Paralogues in human: TMEM47 (30% identical).
Diseases named in the same sentence as PERP in open-access papers:
PERP is named in the same sentence as 45 diseases in open-access papers, as found by Europe PMC text mining. Sharing a sentence is not in itself a finding about the gene and the disease. The quoted sentences say what the papers report.
pancreatic cancer (16 papers, 2020 to 2025). "Pancreatic cancer has a significantly elevated expression of PERP, and PERP serves as a risk factor based on univariate Cox analysis, suggesting an oncogenic role of PERP in pancreatic cancer." (PMID 33748143, 2021). "For example, METTL14 is highly expressed in pancreatic cancer tissues, and the upregulation of METTL14 decreases PERP levels via m6A modification, promoting the growth and metastasis of pancreatic cancer." (PMID 38725005, 2024). "The upregulation of METTL14 has been demonstrated to lead to the decrease of PERP level through m6A modification which promotes the metastasis and growth of pancreatic cancer; thus, METTL14 can be a potential therapeutic target for pancreatic cancer." (PMID 35487915, 2022). "For instance, METTL14 upregulation promotes PERP mRNA N6‐adenosine methylation, facilitating metastasis and growth in pancreatic cancer." (PMID 36264762, 2022). "Targeted adenosine methylation in pancreatic cancer leads to increased PERP mRNA turnover, thereby reducing PERP (mRNA and protein) levels." (PMID 34246319, 2021). "We also demonstrated the critical role of METTL14 in the growth and metastasis of pancreatic cancer via targeting of PERP mRNA." (PMID 32843065, 2020). "Methylation of the target adenosine lead to increased PERP mRNA turnover, thus decreasing PERP (mRNA and protein) levels in pancreatic cancer cells." (PMID 32843065, 2020). "To further examine the association between PERP and METTL14 expression, we performed immunofluorescence assays in pancreatic cancer tissues, and observed that tumor cells with high METTL14 expression showed low PERP expression, and vice versa." (PMID 32843065, 2020). "In this study, we further found that PERP is an essential METTL14 target gene in pancreatic cancer, obviously in an m6A-dependent manner." (PMID 32843065, 2020). "We further provide evidence that METTL14 promotes the growth and metastasis of pancreatic cancer, and identify PERP as an important METTL14 target gene." (PMID 32843065, 2020). "Our data suggest that the upregulation of METTL14 leads to the decrease of PERP levels via m6A modification, promoting the growth and metastasis of pancreatic cancer; therefore METTL14 is a potential therapeutic target for its treatment." (PMID 32843065, 2020). "Interestingly, a recent study showed that knocking down the expression of PERP in pancreatic cancer cells promotes proliferation and invasion of the cells, suggesting a tumor-suppressive function of PERP in pancreatic cancer." (PMID 33748143, 2021). "METTL14 could promote the growth and metastasis of pancreatic cancer by up regulating the m6A level of PERP mRNA." (PMID 34863142, 2021). "Furthermore, the transwell assay revealed that PERP knockdown also significantly counteracted the METTL14 depletion-dependent inhibition of pancreatic cancer cells invasion ability." (PMID 32843065, 2020). "Importantly, since PERP is the major effector through which METTL14 promotes the growth of pancreatic cancer, we suggest it as a potential therapeutic target." (PMID 32843065, 2020).
pancreatic cancer (continued). "Additionally, it was also reported that overexpression of METTL14 could significantly promote the proliferation and metastasis of pancreatic cancer cells in vitro and in vivo via targeting PERP in an m6A-dependent manner." (PMID 38326804, 2024). "In pancreatic cancer cells, METTL14 directly targets the downstream mRNA of PERP, increasing its turnover and decreasing both mRNA and protein levels of PERP, which promotes cancer cell proliferation and metastasis." (PMID 40271153, 2025). "For instance, in pancreatic cancer, METTL14 is upregulated, leading to decreased PERP levels through the m6A‐YTHDF2 axis, thereby promoting cancer growth and metastasis." (PMID 39021049, 2024). "In pancreatic cancer, upregulation of METTL14 expression was reported to lead the reduction of PERP levels via m6A modification, thus promoting the metastasis of PC." (PMID 33849617, 2021). "In addition, we constructed plasmids coding for PERP WT or PERP with a specific 3′-UTR site mutation (that does not prevent PERP expression) and evaluated their impact (after transfection) on the tumorigenic properties of pancreatic cancer cells overexpressing METTL14." (PMID 32843065, 2020). "Overall, mechanistically, METTL14 dysregulation leads to increased m6A modifications in the PERP 3′-UTR, promoting the growth and metastasis of pancreatic cancer." (PMID 32843065, 2020). "We observed that METTL14 overexpression decreased the PERP expression levels and increased the colony formation and invasive abilities of pancreatic cancer cells, treated or not with the construct designed for PERP WT overexpression." (PMID 32843065, 2020). "Based on the transcriptomics profiling of anlotinib in this work and available pancreatic cancer related data deposited in TCGA, GEO, and ICGC databases, we further constructed a prognostic model which consists of five crucial genes, namely TOP2A, CRABP2, CDK1, NUSAP1, and PERP." (PMID 33748143, 2021).
breast carcinoma (12 papers, 2011 to 2025). "DCAF13 has been reported to function as an oncogenic E3 ligase in breast cancer and osteosarcoma by the targeting and degradation of tumor suppressors PERP and PTEN, respectively." (PMID 36359803, 2022). "Trastuzumab also upregulated PERP in EVs emitted by trastuzumab-sensitive breast cancer cells MCF7/Her2-18, a derivative of human breast tumor cells MCF7 producing exogenous ErbB2." (PMID 33023655, 2020). "One of the indicated proteins is PERP that, according to our previous studies, represents an important mediator of ErbB2 signaling: we observed in the past that ErbB2-driven downregulation of PERP is critical for 3D growth of breast cancer cells." (PMID 33023655, 2020). "They provided mechanistic insight into the signaling mechanism of MDA-7/IL-24 and show that the tumor suppressive effects observed in HER2+ breast cancer cells were mediated through PERP, a member of the GAS-3/PMP-22 family of tumor suppressors." (PMID 26474456, 2015). "PERP expression is reduced in many human breast cancer cell lines compared with untransformed cells, and PERP deficiency promotes the development of mammary tumors in mice." (PMID 23071787, 2012). "Previous studies have shown that PERP may act as a tumor suppressor by maintaining adhesion-dependent growth and promoting apoptosis, with well-established roles in melanoma and breast cancer." (PMID 41164195, 2025). "However, importantly, in agreement with the western blotting data based on the cultured cells, we repeatedly observed PERP upregulation by western blotting in EVs derived from the blood of breast cancer patients undergoing trastuzumab-based treatments." (PMID 33023655, 2020). "Our study indicates that levels of proteins PERP, GNAS2, GNA13, ITB1, and RAB10 in EVs emitted by cultured breast cancer cells correlate with sensitivity of these cells to trastuzumab." (PMID 33023655, 2020). "Cotl1 is known to suppress breast cancer growth by activating the IL-24/PERP pathway and inhibiting non-canonical TGFβ signaling." (PMID 39605490, 2024). "Importantly, we observed that PERP, ITB1, GNAS2, and GNA13 are upregulated by trastuzumab in ErbB2-positive human breast cancer cells BT-474 and MCF-7/Her2-18 which indicates that the effect of trastuzumab on these proteins is not unique to one cell line." (PMID 33023655, 2020). "Our data indicate that PERP, GNA13, GNAS2, ITB1, and RAB10 are upregulated in EVs derived from trastuzumab-sensitive but not from trastuzumab-resistant breast cancer cells in culture." (PMID 33023655, 2020). "In summary, we have demonstrated that trastuzumab upregulates PERP, ITB1, GNAS2, and GNA13 in EVs emitted by two different trastuzumab-sensitive breast cancer cell lines but not in EVs derived from two different trastuzumab-resistant breast cancer cell lines." (PMID 33023655, 2020). "Interestingly, unlike the case with EVs, trastuzumab did not upregulate all of the indicated proteins in the breast cancer cells themselves: the drug upregulated RAB10 and PERP in BT-474 cells but downregulated ITB1 and did not change the levels of GNAS2 and GNA13 in the cells." (PMID 33023655, 2020).
lung carcinoma (8 papers, 2021 to 2025). "However, its function in lung cancer remains unclear, and some studies suggest that high PERP expression may be linked to poor prognosis." (PMID 41164195, 2025). "Transwell assays demonstrated that PERP knockdown promoted both migratory and invasive capabilities in lung cancer cells, while colony formation assays showed enhanced proliferative capacity following PERP silencing." (PMID 41164195, 2025). "This feedback loop further augmented the expression of downstream AP-1 target genes, including EFNA5 and PERP, thereby driving lung cancer progression." (PMID 41019373, 2025). "By inducing apoptosis and suppressing VEGF expression, PERP gene therapy was found to attenuate LUAD cell growth in a human lung cancer xenograft model." (PMID 36164607, 2022). "We previously identified PERP-428 SNPs (single nucleotide polymorphisms) PERP-428C and PERP-428G, and found that the antioxidant activity of CL1-0 lung cancer cells expressing PERP-428C was lower than that of cells expressing PERP-428G." (PMID 35011309, 2021). "Moreover, PERP inhibition has been associated with apoptosis and VEGF suppression in lung cancer." (PMID 36900213, 2023). "Stable knockdown of PERP expression induced death of CL1-5 and A549 lung cancer cells." (PMID 39895784, 2025).
uveal melanoma (5 papers, 2012 to 2023). A melanoma derived from melanocytes of the uveal tract. "Preclinical studies have shown that PERP is a critical molecular determinant of apoptosis in primary uveal melanoma, where its downregulation is associated with aggressive disease." (PMID 37509256, 2023). "Downregulation of PERP is associated with the aggressive, monosomy 3-type of uveal melanoma (UM)." (PMID 22759573, 2012). "PERP expression is reduced in human primary uveal melanomas that metastasise, and PERP has been shown to be down-regulated in murine bone marrow-derived mast cells overexpressing microRNA miR-9, which displays increased expression in ‘biologically high grade MCTs’." (PMID 30566430, 2018).
breast tumor (3 papers, 2012 to 2020). "We found previously that ErbB2-driven downregulation of a pro-apoptotic protein PERP in breast tumor cells blocks their anoikis and that various ErbB2 antagonists upregulate PERP in these cells." (PMID 33023655, 2020). "In contrast, trastuzumab failed to upregulate PERP in EVs emitted by ErbB2-positive trastuzumab-resistant human breast tumor cells HCC-1419." (PMID 33023655, 2020). "Thus, trastuzumab upregulates PERP in EVs emitted by trastuzumab-sensitive breast tumor cells but not in those emitted by the trastuzumab-resistant cells." (PMID 33023655, 2020).
melanoma (3 papers, 2013 to 2025). A malignant, usually aggressive tumor composed of atypical, neoplastic melanocytes. "However, it should also be pointed out that additional new genes (IL20RA, HEPB2 and PERP) that are located in this region and are downregulated might make significant contributions to melanoma progression." (PMID 23383013, 2013).
skin cancer (3 papers, 2010 to 2024). "Further studies are required to fully evaluate the role of PERP and Akt in the pathogenesis of skin cancer." (PMID 39201982, 2024). "The primary aim of this study was to evaluate the activation of the PERP and Akt oncogenes in the induction of skin cancer in FVB/N mice by a stepwise chemical process." (PMID 39201982, 2024). "In the context of skin cancer, alterations in PERP and Akt expression and function have profound effects on disease progression." (PMID 39201982, 2024). "Our findings underscore the critical roles of PERP and Akt in the pathogenesis of skin cancer and suggest their potential as biomarkers for early detection and targets for therapeutic intervention." (PMID 39201982, 2024). "To achieve this objective, we conducted a comprehensive immunohistochemical analysis of PERP and Akt expression in a series of chemically induced skin neoplasms, including benign, precancerous, and malignant lesions." (PMID 39201982, 2024). "The primary aim of this study was to investigate the differential expression patterns of PERP and Akt genes in various histopathological types of skin neoplasms in sequential chemical skin carcinogenesis." (PMID 39201982, 2024). "We similarly observe that PERP is lost during human skin cancer development, suggesting that PERP is also important as a tumor suppressor in humans." (PMID 20975948, 2010). "This suggests that although both genes are important in the development of skin cancer, PERP may play a more important role in the early stages of tumor development." (PMID 39201982, 2024). "This study provides a comprehensive analysis of PERP and Akt expression in chemically induced skin carcinogenesis, highlighting significant differences in gene expression across various histopathological stages of skin neoplasms." (PMID 39201982, 2024).